SIRT3 (sirtuin 3)
Diseases named in the same sentence as SIRT3 in open-access papers (continued):
Sharing a sentence is not in itself a finding about the gene and the disease.
acute kidney injury (continued). "According to the previous reports, SIRT3 activation can alleviate ischemia and reperfusion-induced acute kidney injury." (PMID 32490526, 2020). "Two model groups both developed acute kidney injury, while Sirt3-KO mice demonstrated more serious renal dysfunction." (PMID 30445987, 2018). "To investigate the role of Sirt3 in contrast-induced acute kidney injury (CIAKI), we established the model both in vivo and in vitro to explore the potential mechanisms." (PMID 30445987, 2018). "Here, the authors show that human mesenchymal stromal cells, when transplanted into mice with acute kidney injury, stimulate renal tubular cell growth and enhance mitochondrial function via SIRT3." (PMID 29042548, 2017). "Furthermore, SIRT3 mediates the ubiquitination and degradation of mitofusin 2, which inhibits ischemia-reperfusion-induced acute kidney injury." (PMID 40771930, 2025). "Acting as an upstream deacetylase, SIRT3 regulates the acetylation level of pyruvate dehydrogenase E1 component subunit alpha (PDHA1) in renal tubular cells, participating in the occurrence and development of sepsis-associated acute kidney injury (SAKI)." (PMID 39234245, 2024). "Furthermore, activation of Sirt3 by Honokiol increased ATP production as well as reduced ROS and lipid peroxidation by improving fatty acid oxidation resulting in the inhibition of acute kidney injury induced by cisplatin." (PMID 35370645, 2022). "H2S activated SIRT3 through S-sulfhydration to attenuate cisplatin-induced acute kidney injury." (PMID 34603602, 2021). "In addition, SIRT3 deficiency also has a pathogenic effect on acute kidney injury (AKI)." (PMID 34368195, 2021). "Taking together, our findings suggest that Sirt3 deletion may exacerbate contrast-induced acute kidney injury and renal tubular epithelial cells apoptosis in a mouse model of CIAKI as well as in vitro." (PMID 30445987, 2018). "Lactylation of aldehyde dehydrogenase 2 (ALDH2) at lysine 52 (K52la) exacerbates tubular injury and mitochondrial dysfunction in acute kidney injury (AKI), which can be modulated by upregulating SIRT3." (PMID 39737891, 2025). "In accordance with our results, the importance of SIRT3 on mitochondrial-related organ injuries has recently been described in other models of acute kidney injury (AKI)." (PMID 30641872, 2019). "In a CLP-induced sepsis-related acute kidney injury (AKI) mouse model, SIRT3 expression was decreased in renal tubular cells." (PMID 30533222, 2018). "Here, we showed that silybin protected against cisplatin-induced acute kidney injury (AKI) by improving mitochondrial function through the regulation of sirtuin 3 (SIRT3) expression." (PMID 28424621, 2017). "In this study, we used a septic rat model to determine the effects of SIRT1 and SIRT3 on acute kidney injury (AKI) following sepsis." (PMID 28003866, 2016). "Natural product-derived SIRT3 agonists, such as hesperidin (HST) and hepcidin, have shown potential in treating diabetic wounds and acute kidney injury by upregulating SIRT3 expression." (PMID 40872534, 2025). "SIRT3 also modulates fatty acid oxidation by deacetylating liver kinase B1 (LKB1) and activating AMPK to improve cisplatin-induced acute kidney injury (AKI) in mice." (PMID 39372420, 2024). "On the other hand, research on matrine (MAT), which plays multiple pharmacological roles, found that it protected against cisplatin-induced acute kidney injury (AKI) by antioxidative stress and anti-inflammation actions via the SIRT3/OPA1 pathway." (PMID 39765772, 2024). "In a rodent model of sepsis-induced acute kidney injury, a reduction in the activities of SIRT1 and SIRT3 led to heightened acetylation levels of SOD2, accompanied by oxidative stress and mitochondrial impairment." (PMID 39234245, 2024). "Recent studies found that SIRT3 could inhibit mitochondrial fission and promote fusion in the treatment of acute kidney injury (AKI), vitiligo, and Huntington's disease." (PMID 34938344, 2021).
acute kidney injury (continued). "SIRT3 restoration is also beneficial in models of acute kidney injury (AKI)." (PMID 33121167, 2020). "In this study, our results from the western blot and immunohistochemical analysis showed that the contrast-induced acute kidney injury led to the activation of Nrf2 and Sirt3 and that t-BHQ induced the expression of Nrf2 and Sirt3." (PMID 31929854, 2019). "In kidney, SIRT3 has been reported to protect cisplatin-induced acute kidney injury (AKI)." (PMID 28465484, 2017). "In a murine model of acute kidney injury (AKI), cisplatin-induced oxidative injury decreased renal SIRT3 expression and increased mitochondrial fragmentation." (PMID 26370974, 2015). "Treatment with UC-MSCs in mice with cisplatin-induced acute kidney injury (AKI) regulates mitochondrial biogenesis in proximal tubuli by enhancing PGC1α expression, NAD+ biosynthesis and Sirtuin 3 (SIRT3) activity, thus fostering antioxidant defenses and ATP production." (PMID 29042548, 2017).
Sepsis (60 papers, 2016 to 2025). Sepsis is defined as life-threatening organ dysfunction caused by a dysregulated host response to infection. "SIRT3, a mitochondrial deacetylase, emerges as critical in sepsis-induced lung injury, where its loss disrupts Parkin-mediated mitophagy, fueling NLRP3 inflammasome activation via mtROS and mtDNA leakage." (PMID 41026942, 2025). "In sepsis models, genetic ablation of SIRT3 has been associated with intensified apoptotic responses, as evidenced by increased Bax and caspase-3 levels alongside reduced Bcl-2 expression." (PMID 40860195, 2025). "Sirt3 correlated with PCT in the sepsis group and was substantially linked with Scvo2 in the septic shock group, and its levels were negatively correlated with illness severity." (PMID 35729330, 2022). "Sirt3 is a promising biomarker for the diagnosis of sepsis and predicting mortality risk in septic patients." (PMID 35729330, 2022). "Our study suggests that SIRT3 deficiency promotes sepsis-induced AKI via increasing oxidative stress, mitochondrial dysfunction, and inducing apoptosis." (PMID 34249270, 2021). "SIRT3-knockout mice showed increased susceptibility to sepsis, as indicated by elevated small-intestine pathology score and shortened survival time relative to sirt3flox+/+Cre-/- mice." (PMID 33790896, 2021). "Our results indicated that loss of SIRT3 activated oxidative stress in sepsis and aggravated kidney damage." (PMID 34249270, 2021). "Overexpressing of SIRT3 promoted the autophagy and reduced the inflammasomes which are assembling in kidney injury caused by sepsis." (PMID 32175320, 2020). "Here, we further examined the mechanisms underlying the effect of SIRT3 on sepsis-induced AKI, by focusing on the potential involvement and modulation of autophagy by AMPK and mTOR." (PMID 30487750, 2018). "Similar results were obtained for the levels of the proinflammatory cytokines, TNF-α and IL-1β, indicating that SIRT3 knockout increased inflammatory responses associated with sepsis-induced AKI through the AMPK/mTOR/autophagy pathway." (PMID 30487750, 2018). "In conclusion, this study uncovered a potential mechanism underlying the protective role of SIRT3 against sepsis-induced AKI, that involved induction of autophagy through the AMPK/mTOR pathway." (PMID 30487750, 2018). "Using loss- and gain-function approaches, our present study demonstrated a causative relationship between reduction of Sirt3 levels and disruption of angiopoietins/Tie-2 system in the setting of LPS-induced sepsis." (PMID 26868537, 2016). "In summary, our present study revealed novel role of Sirt3 in sepsis-induced pericyte loss and microvascular dysfunction." (PMID 26868537, 2016). "For instance, in sepsis patients, SIRT3 can predict the risk of mortality." (PMID 39091611, 2024). "The effects of PD on Sirt3/NLRP3 pathway associated protein in sepsis mice." (PMID 37494665, 2023). "Sepsis-induced alterations in mitochondrial damage were associated with SIRT3 downregulation." (PMID 28236057, 2017). "It is possible that under high stress conditions, such as those found in sepsis and trauma, Sirt3 may become upregulated and its deficiency would show higher negative impact on the host." (PMID 29236713, 2017). "Surprisingly, knockout of Sirt3 or overexpression of Sirt3 had little effect on LPS-induced loss of capillaries, suggesting that Sirt3 may specific target pericytes in the setting of sepsis and septic shock." (PMID 26868537, 2016). "Additionally, SIRT3 plays a role in sepsis-associated renal damage." (PMID 39544947, 2024). "Similarly, TBM, via SIRT3 modulation, also mitigates sepsis-associated myocardial damage." (PMID 38690282, 2024).
Sepsis (continued). "That Sirt3 deficiency could be responsible for Angpt-2 induction was demonstrated in a model of sepsis showing that knockout of Sirt3 upregulated Angpt-2, accompanied by a severe reduction in pericyte/endothelial cell coverage and exacerbation of vascular leakage." (PMID 37816025, 2023). "Additionally, SIRT3 modulates pericyte loss and vascular dysfunction during early sepsis." (PMID 30216989, 2018). "Melatonin relieves sepsis-induced intestinal injury through SIRT3-mediated reduction of oxidative stress." (PMID 40582762, 2025). "ANXA1sp reduced sepsis-induced MI by increasing SIRT3 expression, which promotes mitochondrial biosynthesis and inhibits oxidative stress as well as autophagy." (PMID 41567643, 2025). "A previous study reported that NMN can prevent mitochondrial dysfunction and alleviate multiorgan failure via SIRT3 signaling in mice with sepsis." (PMID 40046257, 2025). "SIRT3 inhibition exacerbates mitochondrial dynamic imbalance and pro-inflammatory polarization, aggravating sepsis-induced ALI." (PMID 40635757, 2025). "In preclinical models, exogenous melatonin supplementation preserved mitochondrial integrity and activate autophagy, thereby attenuating sepsis-induced multiorgan dysfunction through SIRT3 upregulation." (PMID 40860195, 2025). "SIRT3 abolishes sepsis-induced ALI via pyroptosis inhibition, which are crucial in mitigating inflammation and oxidative stress in ALI." (PMID 40635757, 2025). "Activation of SIRT3 attenuates the sepsis-induced AKI by modulating the AMPK/mTOR signaling to enhance autophagy." (PMID 38345033, 2024). "Downregulation of SIRT3 expression in renal tissues and HK-2 cells after sepsis results in an elevation of PDHA1 acetylation levels coupled with diminished PDHA1 activity." (PMID 39234245, 2024). "Recent studies have expanded the spotlight from SIRT1 to include SIRT3 as a crucial participant in the protective effects of melatonin against sepsis-induced MODS." (PMID 38690282, 2024). "For instance, the extent of reduction in serum levels of SIRT3 can differentiate between sepsis and septic shock patients and is well correlated negatively with the SOFA score." (PMID 38690282, 2024). "In LPS-stimulated macrophages, overexpression of SIRT3 through SDHA deacetylation, mitigates sepsis-associated aerobic glycolysis.The role of SIRT4 in inflammatory immune responses is not entirely clear yet." (PMID 38690282, 2024). "Extensive vascular endothelial dysfunction often occurs in early sepsis, and SIRT3 plays an important role in its pathogenesis." (PMID 39564112, 2024). "In models of sepsis-induced endothelial dysfunction, the expression of SIRT3 is significantly reduced, whereas TBM treatment reversed this trend, enhancing SIRT3 expression." (PMID 38690282, 2024). "We observed that LPS increased apoptosis, induced disturbances in mitochondrial function and dynamics, and downregulated Sirt3 expression in a sepsis‐induced AKI mouse model and human proximal tubular (HK‐2) cells in vitro." (PMID 36433732, 2023). "Melatonin alleviates sepsis-induced cardiac dysfunction by increasing the SIRT3-mediated deacetylation of Beclin1 and promoting autophagy." (PMID 37754811, 2023). "This study has also delineated molecular mechanisms underlying NMN’s therapeutic effects in sepsis: NMN prevents mitochondrial dysfunction and oxidative stress through SIRT3 signaling by boosting NAD+." (PMID 38057866, 2023). "NAD+ repletion with NMN prevents mitochondrial dysfunction and restrains bacterial dissemination while limiting inflammatory damage through SIRT3 signaling in sepsis." (PMID 38057866, 2023). "Plantainoside D (PD), an effective component of Plantago asiatica L., significantly improved sepsis induced ALI by regulation of Sirt3/NLRP3 pathway." (PMID 37494665, 2023).
Sepsis (continued). "Through proteomic technology, this study found that there were 38 differentially expressed proteins in the lung tissues of sepsis mice and control mice, of which Sirt3 had the most significant difference, and the expression was significantly down-regulated." (PMID 37494665, 2023). "A recent study reported that decreased NAD+ impaired SIRT3 function in sepsis, leading to mitochondrial dysfunction." (PMID 38057866, 2023). "SIRT3 plays an essential role in refeeding syndrome-related myocardial injury during lipopolysaccharide-induced chronic sepsis in rats, possibly via the regulation of PINK/Parkin-mediated mitochondrial autophagy." (PMID 37754811, 2023). "We divided the patients into low Sirt3 (< 15.33 pg/ml) and high Sirt3 (≥ 15.33 pg/ml) groups, with 25 patients in the low Sirt3 group (13 sepsis and 12 septic shock) and 26 patients in the high Sirt3 group (22 sepsis and 4 septic shock)." (PMID 35729330, 2022). "Recently, exosomal circ-Fryl derived from ADSCs has been shown to play a protective role in sepsis-induced lung injury by regulating the miR-490-3p/SIRT3 axis." (PMID 35700140, 2022). "Sirt3 not only performed well in identifying sepsis (AUC = 0.995, 95% CI 0.987–1, P < 0.0001) but also greatly enhanced lactate's specificity in detecting septic shock (from 91.43 to 94.29%)." (PMID 35729330, 2022). "In the future, we hope for bigger multicenter follow-up cohort studies to look into the role of Sirt3 in sepsis." (PMID 35729330, 2022). "Sirt3 performed better in identifying sepsis (AUC = 0.995, 95% CI 0.987–1, P < 0.0001) than SOFA (AUC = 0.968, 95% CI 0.934–0.1, P < 0.0001), PCT (AUC = 0.925, 95% CI 0.865–0.985, P < 0.0001)." (PMID 35729330, 2022). "The serum levels of Sirt3 were lower in the sepsis patients on day 1 (P < 0.0001), and the septic shock group had lower Sirt3 levels than the sepsis group (P = 0.013)." (PMID 35729330, 2022). "The serum level of Sirt3 was lower in septic patients on day 1 (P < 0.0001), and the septic shock group had a lower level than the sepsis group (P = 0.013)." (PMID 35729330, 2022). "We found that oxidative-stress alleviation by melatonin is closely related to SIRT3 activation in sepsis-induced small-intestine injury." (PMID 33790896, 2021). "SIRT3 can also protect against sepsis-induced AKI by promoting autophagy via upregulating p-AMPK and downregulating phosphor-mammalian target of rapamycin (p-mTOR)." (PMID 34220520, 2021). "Although we did not further investigate the mechanism by which melatonin enhances autophagy, our results emphasize the role of SIRT3 activation in melatonin-dependent protection against sepsis-induced small-intestine injury." (PMID 33790896, 2021). "Nevertheless, our study has emphasized the key role of SIRT3 in melatonin-mediated protection against sepsis-induced small-intestine injury." (PMID 33790896, 2021). "Fourth, we believe the mechanism of melatonin-mediated SIRT3 activation in ameliorating sepsis is not limited to SOD2 deacetylation and warrants comprehensive investigation in the future." (PMID 33790896, 2021). "To investigate the effect of SIRT3 on oxidative stress during sepsis-induced AKI, we used immunohistochemistry to detect iNOS protein expression." (PMID 34249270, 2021). "We identified for the first time Sirt3 as the crucial mediator of sepsis-induced lung microvascular endothelial barrier integrity." (PMID 34630854, 2021). "Although a limited number of studies show the specific role of SIRT3 in sepsis, SIRT3 plays an important role in mitigating inflammation in general, oxidative damage, and organ dysfunction." (PMID 35052507, 2021). "Consistent with the CLP-induced sepsis model, treatment with rATRAM-GRA8-M/AS considerably enhanced the association of rGRA8 with ATP5A1, SIRT3, and ATP5C1." (PMID 32002124, 2020). "It has been demonstrated that SIRT3 protects against AKI induced by ischemia-reperfusion, sepsis, and cisplatin, while SIRT3-deficient animals had more severe AKI and decreased survival rate." (PMID 30641872, 2019).